CD38 (CD38 molecule)
Diseases named in the same sentence as CD38 in open-access papers (continued):
Sharing a sentence is not in itself a finding about the gene and the disease.
leukemia (continued). "With this identification it was determined that only cells that were located in the CD34+/CD38- population of progenitor cells had the capacity to initiate leukemia in NOD-SCID mice when compared with CD34- and CD34+/CD38+ cells." (PMID 21439058, 2011). "Treatment of SCID/CEM mice with a single IT containing the parental murine IgG1 anti-CD7 or anti-CD38 led to a delay in the development of leukemia, but 90% of animals treated with either IT developed disseminated leukemia cell growth." (PMID 22069735, 2011). "For example, CD34+CD38- cells in leukemia, CD44+CD24low/lin- cells in breast cancer and CD133+ cells in brain and prostate tumors." (PMID 19744348, 2009). "This includes for example for bendamustine ARID5B associated with susceptibility of childhood acute lymphoblastic leukemia and treatment outcome, CD38 associated with cell survival and proliferation in chronic lymphocytic leukemia, and the oncogene MYB involved in different leukemias." (PMID 41146244, 2025). "Additionally, the immunophenotypic strategy employed showed a high specificity, with lymphoblastic cells consistently expressing established leukemia-associated markers and a distinctive CD34++CD38−/dim expression profile." (PMID 40076750, 2025). "Importantly, patients with CD34+CD38- leukemia cells with high ALDH activity manifest a significantly lower complete remission rate, as well as poorer event-free and overall survival." (PMID 40643557, 2025). "Furthermore, these WT1-CTLs effectively killed AML cells with a CD34+/CD38− immunophenotype, a cell compartment which is classically enriched with leukemia-initiating cells [(LICs) or leukemic stem cells (LSCs)]." (PMID 39711535, 2024). "Notably, elevated PRMT9 protein levels were seen in an LSC-enriched (CD34+CD38−) relative to a leukemia committed progenitor (CD34+CD38+) subset or to either of the normal subsets." (PMID 38413714, 2024). "Therefore, identifying CD34+/CD38+/CD19+ self-renewing B-ALL cells introduces a hierarchy of leukemia-initiating cells that differ from AML." (PMID 37692500, 2024). "They showed that the CD34+/CD38- cell subpopulation from acute myeloid leukemia could form leukemia after transplantation into NOD.SCID mice." (PMID 37284445, 2023). "In the case of the relapsing leukemia reported here, the separation of malignant cells from background lymphocytes based on CD38, CD10 and CD20 expression allowed for the immediate assignment of IG/TR markers to malignant cells, both at diagnosis and at relapse." (PMID 37958202, 2023). "CD34+CD38− lymphoblasts as likely leukemia stem cells (LSCs) may be responsible for a worse response to treatment and may be a risk factor for recurrence in B-cell precursor acute lymphoblastic leukemia (BCP-ALL)." (PMID 37675394, 2023). "The first leukemia-initiating cells (LICs) were discovered in the CD34+CD38− section of AML cells." (PMID 37735675, 2023). "In leukemia, a CD38‐negative CD34‐positive phenotype has been associated with increased adherence, dormancy, stem‐like features, and therapy resistance." (PMID 35271751, 2022). "The use of NSG PDX models has also led to a better understanding of the heterogeneity of leukemia-initiating cells (LIC) as reports identified the existence of not only CD34+CD38- LIC cells but also CD34+CD38+ and even CD34- populations capable of initiating AML." (PMID 35756660, 2022). "In CD34+/CD38- leukemia stem cells, we found that MK256 induced differentiation and maturation." (PMID 36342456, 2022). "Here, we show BK124.1 efficacy against the human CML cells in a xenotransplantation mouse model and in the two groups of particularly resistant cells: K562 cells expressing MDR1 (K562-MDR1) and in CD34+/CD38- leukemia stem cells from peripheral blood of CML chronic phase patients." (PMID 35892900, 2022).
leukemia (continued). "As expected, genes associated with AML proliferation (FLT3, KIT), leukemia stem cells (CD34, CD38, and IL1RAP), and candidate genes overexpressed in AML (CD99, CD200, and LAMP2) were downregulated after chemotherapy, consistent with recent scRNA-Seq and immunohistochemistry data." (PMID 36099049, 2022). "Cell surface proteins are used as CSC markers for different types of tumors, for example, cluster of differentiation 34-positive (CD34+)/CD38 − for leukemia cells, CD13/CD45/CD90 for liver cancer, CD117/CD90/epithelial cell adhesion molecule for lung cancer, and CD44 for colon and gastric cancers." (PMID 35148781, 2022). "This adjuvant increased CD38 density on the surface of these leukemia cells." (PMID 34203012, 2021). "LSCs have a self-renewal capacity to generate large numbers of leukemia progenitor cells (CD34+CD38+) through the activation of several signaling pathways including WNT/β-catenin, Hedgehog (Hh), Notch, transforming growth factor-β (TGF-β)/Forkhead box O (FOXO), and Musashi 2 (Msi2)-Numb signaling." (PMID 34922630, 2021). "Besides, the high expression and activation of viral integration site 1 (EVI1) in CD34+CD38– stem cells leads to increase self-renewal capacity, leukemia development and the disease progression to BP." (PMID 34922630, 2021). "In addition, the expression of IL-10R on leukemia stem cells (CD34+ CD38−) was lower than that on bulk blast cells." (PMID 34392305, 2021). "Multiple studies have shown that leukemia stem cells (LSCs) in AML immunophenotypically resemble committed progenitor cells such as lymphoid-primed multi-potent progenitors (LMPPs) (Lin-CD34+CD38-CD90-CD45RA+) or GMPs (CD34+CD38+CD123+/loCD110-CD45RA+)." (PMID 35822030, 2021). "However, later findings indicate that Fc-mediated clearance of anti-CD38 conjugated cells was responsible for the low leukemia initiating cell (LIC) activity that had been observed in the CD34+/CD38+ fraction." (PMID 34736527, 2021). "Among these, CD34−/CD38+ as well as CD34−/CD38− subpopulations induced leukemia." (PMID 33322769, 2020). "Importantly, immunohistochemical examination confirmed infiltration of CD34+/CD38+ blasts in the spleen, consistent with aggressive leukemia development in vivo." (PMID 33163905, 2020). "We investigated the effects of six small molecule pharmacological agents, which interfere with endocytic and other processes, on SA-mediated augmentation of saporin and saporin-based immunotoxins (ITs) directed against CD7, CD19, CD22 and CD38 on human lymphoma and leukaemia cell lines." (PMID 30791598, 2019). "The cells of CD34+ primary leukemia and CD38- KG-1, and TF-1 were separated by flow cytometry." (PMID 31307525, 2019). "In one study, characterization of 5 AML samples via Affymetrix Hu133A microarrays allowed the identification of 261 DNA repair, signal transduction and cell cycle genes, the expression of which was significantly lower in AML-derived LSCs compared with CD34+CD38+ leukemia cells." (PMID 29466292, 2018). "Similarly, previous studies have reported that in B-ALL, only CD34+CD38− cells can initiate leukemia in immunodeficient recipients." (PMID 28018598, 2016). "Studies from clinical data and experimental systems have shown that AML originates from a rare population of LSCs (CD34+CD38- cells) or leukemia-initiating cells (LICs) which are capable of self-renewal, proliferation, and differentiation into malignant blasts." (PMID 27917123, 2016). "Interestingly, Ouabain was shown to be more effective at targeting the CD34+CD38− leukemic stem cell-like population than the CD34+CD38+ leukemia cells, which makes this type of compounds an interesting potential anti-LSCs drug candidate." (PMID 27110755, 2016). "CD38, an established cell-surface glycoprotein on leukocytes, is a prognostic marker of leukemia." (PMID 25543152, 2015).
leukemia (continued). "Aberrantly high expression of TWIST-1 in leukemia stem/progenitor cells could be confirmed when we analyzed the expression of TWIST-1 in highly purified leukemic CD34+CD38−, CD34+CD38+ and CD34− cells isolated from patients with AML (n = 9) and CML (n = 9)." (PMID 26023795, 2015). "Therefore, we first isolated LSCs using magnetic sorting with the gold standard surface markers CD34 + CD38- from six leukemia cell lines." (PMID 25890196, 2015). "However, cancer initiating cells in other neoplasms have been characterized by at least 2 different surface markers; CD44+/CD24-/lin- in breast cancer, a2b5+/CD133- in glioblastoma and CD34+/CD38− in leukemia:." (PMID 25105565, 2014). "In order to assess whether these were clinically important, when present together with the leukemia initiating CD34+CD38- compartment, we assessed their prognostic impact." (PMID 25244440, 2014). "Furthermore, the coexpression of CD31 and its ligand CD38, on plasma cells suggests a role for this interaction in the plasma cell survival niche as already proposed for leukemia cells." (PMID 25759831, 2014). "Hence, our data confirm that a DNA damage response can be induced in dormant CD34+CD38- leukaemia cells." (PMID 23013471, 2012). "The CD34+CD38- cell subset was originally thought to contain all the leukaemia initiating cells." (PMID 23013471, 2012). "CD38 is strongly expressed by myeloma, lymphoma and leukemia cells." (PMID 22069735, 2011). "Interestingly, though the proportions of sGRP78+ cells coexpressing CD34, CD38, CD10 or CXCR4 were significantly higher in High-risk leukemia population, these samples showed the presence of a subgroup of double positive cells rather than a general increase of the positivity to the analyzed markers." (PMID 35149705, 2022). "Furthermore, alantolactone was more toxic to CD34+CD38– cells than total primary leukemia cells." (PMID 27658462, 2016). "Indeed, recent work has shown that CK2 inhibition dampens down the PI3K/AKT pathway with a reduction of the activity of downstream effectors such as Bcl-xl and NF-κB and cooperates with PI3K inhibitors in inducing cell death of CD34+ CD38- AML leukemia stem cells." (PMID 24283803, 2013). "In addition, the incubation of leukemia cells with antibodies targeting surface markers, such as anti-CD38, may reduce the engraftment capacity of leukemia-initiating cells expressing these markers, even further complicating the analysis of human LSCs." (PMID 24427158, 2013). "Thus they concluded that CD34+CD38- subpopulations were the initiating cells of leukemia." (PMID 21542915, 2011). "The metabolism of NAD+ through ectoenzymatic pathways relies on adenosine‐generating enzymes CD38 and CD73, potentially contributing to tumor development, including leukemia." (PMID 40285538, 2025). "By using cell surface markers, CD34 and CD38, which identified progenitor and pluripotent stem cells in bone marrow, AML-initiating cells that produced leukemia when transplanted in immunodeficient mice were observed to be CD34+CD38− cells." (PMID 39335624, 2024). "In human acute myeloid leukemia, the existence of leukemia stem cells (LSC) is well-established and shown to be phenotypically restricted to CD34+CD38-cells." (PMID 37173970, 2023). "Results indicated that LY/Api synergistically enhanced apoptosis in leukemia cells, particularly CD34+CD38− leukemia cells." (PMID 36984844, 2023). "went on to further show that TWIST1 was most highly expressed in the putative leukemia stem cell (LSC) compartment in AML (CD34+CD38-) and that its expression in LSCs was higher than in normal CD34+CD38- HSCs." (PMID 37600794, 2023). "We chose CD19 or CD38 as second tumor target, because both antigens are co-expressed with CD20 on a variety of B cell lymphomas or leukemias making these tumor antigen combinations ideal for the dual-dual-targeting approach." (PMID 37965326, 2023).
leukemia (continued). "In a phase 1/2 trial for CD38 CAR T in AML, the median leukemia-free survival (LFS) time was 6.4 months with manageable side effects." (PMID 36139103, 2022). "A robust engraftment of primitive CD34+CD38- leukemic progenitors, also known as NOD/SCID leukemia-initiating cells (NOD/SL-IC) or leukemic stem cells (LSC), was observed in NOD/SCID mice." (PMID 35756660, 2022). "Four weeks after anti-CD38 CAR-T cell infusion, 4/6 patients (66.7%) achieved CR or CRi, with a median time to CR or CRi of 191 days, a median OS of 7.9 months, and a median leukemia-free survival (LFS) of 6.4 months." (PMID 36313735, 2022). "An older study of this syndrome showed that in people with the CD38+ phenotype who had lower CTLA-4 expression, leukemia had a mild course." (PMID 35158937, 2022). "Next, western blotting analysis was revealed that PTL decreased the levels of caspase 3 and increased the levels of activated caspase 3 and PARP in differentiated leukemia cells (CD34-CD38+) and LSCK562/ADM (CD34+CD38-)." (PMID 34405014, 2021). "CSCs were first identified in a leukemia model, in which CD34+CD38− leukemic cells showed the characteristics of bone marrow hematopoietic stem cells." (PMID 34671679, 2021). "The leukaemia PDX models were characterized by a definite expression pattern of surface markers determined by FC: CD45, CD34 and CD38 were expressed in a model specific percentage on the tumour cells." (PMID 32466316, 2020). "To establish the detection limit and sensitivity threshold of dSTORM and FC, we performed antibody titration experiments on the human leukemia cell line NALM-6, which uniformly expresses CD19 (phenotype: CD19+CD38+CD138+)." (PMID 31316055, 2019). "qPCR analysis demonstrated that Nanog mRNA levels were significantly higher in CD34+ leukemia cells than in CD34- counterparts, and overexpressed in LSCs (CD34+CD38-)." (PMID 30013477, 2018). "CD34+CD38− cells can initiate leukemia efficiently, but CD34−CD38+ cells cannot, showing the existence of leukemia stem cells." (PMID 30310855, 2018). "In order to investigate the efficacy of ATP treatment in leukemia stem progenitor compartment, we first examined P2×7R expression in four different LSC subsets: CD34-CD38-, CD34+CD38-, CD34+CD38+, CD34-CD38+." (PMID 27980223, 2017). "In this preclinical setting, we further demonstrated that a low dose of chidamide can sensitize conventional chemotherapeutics to leukemia stem cell-like cells, including CD34+CD38− KG1α cells, CD34+CD38− Kasumi cells, and primary AML stem/progenitor cells." (PMID 28814980, 2017). "Analogous results were obtained in leukemia stem-like cells sorted from Kasumi-1 cells, another human AML cell line, with 92.7±3.1% of CD34+/CD38− cells." (PMID 28518151, 2017). "Initial reports described a specific cell surface phenotype for LSCs that allowed primitive leukemia cells to be distinguished from normal stem and progenitor cells (CD34+, CD38-, CD123+ and so on)." (PMID 28114350, 2017). "Here, we identified the role of miR-150 in proliferation and tumorigenicity in leukemia stem cells (LSCs; CD34+CD38- cells)." (PMID 27917123, 2016). "By intravenously injecting purified CD34+CD38+CD19+ or CD34+CD38−CD19+ cells from B-precursor ALL patients, they successfully demonstrated the leukemia-initiating capacity of both cell types." (PMID 28018598, 2016). "CD34 and CD38 expression were detected in most B-ALL and can serve as a specific biomarker for the prognosis of this subset of leukemia." (PMID 28018598, 2016). "We have recently shown that CD34+/CD38- AML cells are in a dormant state and are more refractory to the anti-leukemia agent, cytarabine, than mature CD34+/CD38+ AML cells." (PMID 25955299, 2015). "The CD34+CD38+ and CD34- compartments have been shown to contain leukemia initiating cells (also in this paper)." (PMID 25244440, 2014).
leukemia (continued). "Nilotinib particularly targets CD34+CD38− stem cells and MDR leukemia cells, and effectively enhances the efficacy of chemotherapeutic drugs by blocking the efflux function of ABC transporters." (PMID 24651611, 2014). "In contrary, other investigators have shown that CD34+CD19+CD38± cells sorted from patients’ BM were able to initiate leukemia in NSG mice, had self-renewal properties, and resulted in lethal CD19+ leukemia in the host." (PMID 24847444, 2014). "Taken together, these data suggest that nilotinib particularly targets CD34+CD38− stem cells and MDR leukemia cells, and effectively enhances the efficacy of chemotherapeutic drugs by blocking the efflux function of ABC transporters." (PMID 24651611, 2014). "On the other hand, in more severely immune-compromised mouse models, CD34+CD38+ and CD34-negative compartments were also found to contain leukemia initiating cells." (PMID 25244440, 2014). "LSCs are often phenotypically defined as simply the CD34+ leukemia cells or, more recently, the more enriched CD34+CD38− subset, but even the CD34+CD38− cells are a heterogeneous population of which the LSCs constitute only a fraction." (PMID 23651669, 2013). "To study the effects of leukemia cells on BMSCs, we co-cultured BMSCs from healthy donors with three different leukemia cell lines, TF-1α, TF-1 and K562, that were selected according to their phenotypes: CD34+/CD38-, CD34+/CD38+ and CD34-, respectively." (PMID 24304929, 2013). "CLO-TOR was pro-apoptotic in an AML patient blast subset (CD34+/CD38−/CD123+), which is enriched in putative leukemia initiating cells (LICs)." (PMID 23271044, 2012). "Strikingly, remission patients have much lower transition rates into the CD34+/CD38− and CD34−/CD38− cell states than corresponding samples from patients with leukemia not in remission." (PMID 41295979, 2026). "Instead, the results favor a nonhierarchical relationship between the leukemia stem cell compartment (CD34+/CD38−) and other cell states, such that the mathematical modeling predicts that it is possible to access all cell states from any cell state." (PMID 41295979, 2026). "Further immunophenotyping of these CD34+ MRD specimens indicated low expression or the absence of CD38 expression, which is consistent with an immature, leukemia-regenerating cell phenotype." (PMID 40609795, 2025). "A significant reduction in BM cellularity, leukemia burden in PB and leukemia, as well as LSC (CD34+CD38− and CD34+CD38+ cells) burden was observed in end-study organs of CLL1CART-treated mice compared to negative controls after sequential treatment with CLL1CART." (PMID 40268927, 2025). "The presence of the CD34+ antigen and the absence of CD38−, assessed by the authors, is taken into account in the identification of leukemia stem cells." (PMID 37675394, 2023). "Additionally, CSCs in leukemias are often characterized by the expression of specific cell surface markers, such as CD34, CD38, and CD123, among others, which can be isolated to study CSC populations in leukemia samples." (PMID 37614497, 2023). "LY/Api also resulted in the notable downregulation of anti-apoptotic proteins, such as NF-κB, and Bcl-xL in CD34+CD38− leukemia cells, but not in healthy HSCs." (PMID 36984844, 2023). "Notably, Isa demonstrated potent antitumor activity against diverse CD38+ B‐cell lymphoma, DLBCL, MM, and leukemia cell lines as well as xenograft models derived from these cell lines." (PMID 36251503, 2023). "Moreover, it is now possible to detect antibodies present in leukemia cells, such as CD52, CD38, CD33, CD20, CD25, CD19, and CD22, and target them with new antibody–drug conjugates." (PMID 35011701, 2022). "From another study, the expression of human ether‐a‐go‐go‐related gene (hEGR) K+ channel is observed in a subpopulation (CD34+CD38–CD123high) of leukemia cells but not in normal bone marrow CD34+/CD38– HSPCs." (PMID 34786735, 2022).